CD96 (CD96 molecule)
Diseases named in the same sentence as CD96 in open-access papers (continued):
Sharing a sentence is not in itself a finding about the gene and the disease.
tumor (continued). "Therefore, preclinical studies employed inhibitory anti-CD96 monoclonal antibodies (mAbs) to study their potential to induce anti-tumor immunity." (PMID 36140247, 2022). "Specifically, we hypothesized that by inhibiting BCL9 activity, we could shift the balance of CD226 and CD96 checkpoints towards more cytotoxicity and thereby impede tumor growth." (PMID 34417435, 2021). "TIGIT and CD96 are expressed on the surface of T cells and natural killer cells and represent targets for immune modulation, as blocking CD96 or TIGIT with monoclonal antibodies improves tumor control in mice, especially when used in combination with PD-1/PD-L1 blockade." (PMID 33796453, 2021). "TIGIT and TACTILE/CD96 are inhibitory co-receptors expressed by both T and NK cells, and are linked to the CD112 (Nectin-2) and CD155 (PVR) expressed by APCs, infected cells and tumor cells." (PMID 34359767, 2021). "In addition, tumor-bearing mice treated with anti-PVRIG mAb showed lower frequency of tumor-infiltrating CD8+ T cells expressing inhibitory receptor CD96 and higher frequency of tumor-infiltrating CD8+ T cells expressing NKG2D, TRAIL, CD107a, GzmB and IFN-γ." (PMID 34174928, 2021). "Meanwhile, emerging evidence showed that therapies targeting PVR/TIGIT/CD96 pathways could enhance anti-tumor capacity across certain cancer types." (PMID 34150627, 2021). "Study has suggested that CD96 could synergize with TIGIT to inhibit the antitumor response in tumor-bearing mouse models with lung metastasis, as the antitumor effect of CD96 blockade is higher in Tigit−/− mice." (PMID 33680972, 2021). "Finally, the relationships between CD96 expression and tumor purity were significant in CESC, COAD, and ESCA." (PMID 33680972, 2021). "CD155 is another immune checkpoint protein, expressing on tumor cells and interacts with CD96, CD226, and T cell immunoreceptor with immunoglobulin and ITIM domains (TIGIT) on tumor-infiltrating lymphocytes to modulate the immune function in tumor immune microenvironment." (PMID 32411795, 2020). "Although it remains unclear whether increased sCD155 production is a cause of tumor development, sCD155 may modulate tumor immune responses through interaction with any, or all, of DNAM-1, TIGIT, and CD96 on T cells and NK cells." (PMID 32040157, 2020). "Emerging data has demonstrated a critical role for CD96 in tumor immunology." (PMID 32612110, 2020). "CD155 is a ligand for DNAM-1, TIGIT, and CD96 and is involved in tumor immune responses." (PMID 32040157, 2020). "Moreover, the high CD96 levels in tumor tissues correlated with the shorter overall survival and disease-free survival." (PMID 32714324, 2020). "Moreover, Smyth’s group demonstrated that disrupting the interaction between mCD96 and mCD155 by using anti-CD96 blocking antibodies, metastatic spread was inhibited in several tumor models." (PMID 32019260, 2020). "Indeed, an important mechanism of immune evasion involves decreased activating DNAM-1 and increased inhibitory TIGIT/CD96 expression on tumor infiltrating immune cells." (PMID 32069911, 2020). "Likewise, another study described a role of CD96 in constraining NK cell-mediated suppression of tumor metastasis in mice." (PMID 31340613, 2019). "Although the role of TIGIT and CD96 as immune checkpoint receptors are just beginning to be uncovered, accumulating data would support the notion that targeting of these receptors for improving anti-tumor immune responses also involves NK cells and ILCs." (PMID 31105707, 2019). "CD155 is the main ligand for TIGIT and CD96, and is highly expressed on many types of tumor cells." (PMID 30250471, 2018). "The findings therefore indicate that CD226 and CD96 could contribute to NK cell dysfunction and thereby induce PC progression and tumor immune escape." (PMID 27626490, 2016).
tumor (continued). "The relative increase in active signal receipt via CD96 may represent compensatory means of tumor immune evasion as cancer cells, CAFs, TAMs, DCs, and mast cells were all found to express PVR and NECTIN1 within our dataset, both of which are capable of inducing immunosuppression in CD8+ T cells." (PMID 39811671, 2025). "Signaling in this pathway might not only be directed from APCs or tumor cells toward CD96-expressing T cells and NK cells but there might also be a tumor cell-derived modification of APC-dependent cytokine production toward immunosuppression via T and NK cells as interim players." (PMID 37046787, 2023). "There is evidence that a blockade of CD96 might positively affect the anti-tumor immune response." (PMID 37046787, 2023). "Using CD96-deficient mice, some of these studies demonstrated that CD96 limited the production of interferon-γ (IFN-γ) by NK cells, but not their cytotoxic function, the former being important for tumor control in two independent models of carcinogenesis and metastasis." (PMID 36672244, 2023). "Interestingly, a fraction of cytokeratin (CK)+ tumor cells were strongly positive for CD96." (PMID 36581470, 2023). "Consistently, the Tyr75Ala mutation in tumor cells with low CD96 expression promotes chemotherapy efficiency in vivo rather than the Gln46Ala mutation, which was assessed by tumor size and 18F‐flourodeoxyglucose (18F‐FDG) Positron Emission Tomography/Computed Tomography (PET‐CT)." (PMID 36581470, 2023). "Interestingly, whereas low anti-PD-1 exposure in animals treated with anti-PD-1 alone allowed the tumor to grow fast (A13), a similar low exposure in the combination group (A31, 33 and 34) showed regression in tumor growth, although anti-CD96 levels were below LLOQ." (PMID 36140247, 2022). "Furthermore, we evaluated whether CD96 is coexpressed with the inhibitory receptor PD-1, typically found on chronically stimulated and/or exhausted tumor-infiltrating CD8+ T cells." (PMID 35998045, 2022). "However, CD96−/−CD8+ T cells in mice promote tumor growth more than CD96-sufficient CD8+ T cells." (PMID 34433460, 2021). "In addition, CD8_1 and CD8_2 had respectively increased levels of PD-1 and CD96 in tumor samples." (PMID 34921160, 2021). "Therefore, whether CD96 activates NK cells to exert tumor cell killing effect or inhibits its activity is still inconclusive." (PMID 33680972, 2021). "The lower expression of CD226 and CD96 on NK cells may be contributing to tumor escape." (PMID 33946954, 2021). "Furthermore, CD96 protein expression was extremely low in all cancer tissues, with moderate CD96 cytoplasmic positive expression observed only in a subset of lymphoid cells within the tumor stroma." (PMID 33680972, 2021). "Interestingly, a recent publication suggested that platelet-cloaked tumor cells might suppress expression of CD96 on the NK cell surface." (PMID 34503073, 2021). "In conclusion, both TIGIT and CD96 were demonstrated to negatively regulate NK cell activity, and preventing the binding of these receptors with their ligands could benefit NK cell-mediated anti-tumor functions." (PMID 33572396, 2021). "Specifically, CD96 showed a positive correlation with T-helper 1/2 type immune response (GO:0042088 and GO:0042092), T-helper 1/2 cell cytokine production (GO:2000556 and GO:2000553), and NK cell-mediated cytotoxicity directed against tumor cell target (GO:0002860)." (PMID 32695752, 2020). "However, one should consider that CD96, as ambiguous as its functions seem to be in humans, might participate in the inhibition of an anti-tumor response." (PMID 32489646, 2020). "Thus, neutralizing TIGIT/CD96 alone or in combination with other agents might be a potential strategy to improve anti-tumor immunotherapy by NK cells." (PMID 31340613, 2019).
tumor (continued). "Our results suggest that a lower percentage of CD226+ and CD96+ NK cells may contribute to tumor immune escape in PC patients; moreover, the use of NK cells with high CD226 and CD96 expression to treat PC cells with high CD155 expression may have potential and should be explored in the future." (PMID 27626490, 2016). "CD155, an immune checkpoint molecule interacted with receptors of TIGIT/CD96/CD226 to exhibit co-inhibitory and co-stimulatory modulation on tumor immune microenvironment." (PMID 41181119, 2025). "TIGIT, CD226, CD96 and PVRIG are expressed on T and NK cells, whereas CD155 (PVR) is often overexpressed on tumour cells." (PMID 41462864, 2025). "The signalling function of CD96 remains elusive in humans, while NKG2D provides activating signals to NK cells after binding its ligands on tumour cells." (PMID 40510180, 2025). "In the ccRCC dataset, macrophages demonstrated robust signaling capabilities within the tumor microenvironment, engaging in various pathways including COLLAGEN, APP, and CD96." (PMID 41488617, 2025). "With CD155 binding, TIGIT/CD96/CD226 transmits inhibition and activation signals to the immune system, and the integrated signals regulate immune functions and affect the anti-tumor immune response." (PMID 41181119, 2025). "CD155 was detected on TME tumor cells (TC) and TIGIT/CD96/CD226 were detected on both TC and stromal tumor-infiltrated lymphocytes (TILs)." (PMID 41181119, 2025). "CD96, CTLA-4, and PDCD-1 are important immune checkpoint proteins that play a crucial role in tumor immune evasion." (PMID 40746529, 2025). "TIGIT, DNAM-1 (CD226), CD96, and CD112R are expressed on T cells and natural killer (NK) cells, while their ligands—CD155, CD112, CD113, and CD111—are expressed on APCs or tumor cells." (PMID 40356928, 2025). "To explore the potential impact of the tumour microenvironment on immune homeostasis between TIGIT, CD96 and CD226 in LUAD, we performed correlation analyses among these three receptors." (PMID 38279870, 2024). "Together, these findings suggest that TIGIT expression is upregulated on both CD96+CD8+ T cells and CD226+CD8+ T cells within the tumour microenvironment of LUAD." (PMID 38279870, 2024). "In this context, cleavage of CD96, TIGIT, or DNAM1 in tumour-infiltrated lymphocytes cannot be excluded in response to TT." (PMID 38891113, 2024). "Upon inhibition of CD96, the population of IFN-γ+ T cells and their cytokine secretion significantly increases, resulting in tumour suppression." (PMID 38893071, 2024). "On the other hand, the communication patterns of the target cells suggested that incoming tumor epithelial cell signalings were dominated by mode 1, which included signaling pathways such as CD99 and MK, as well as PTN, CEACAM, CD96, and GRN." (PMID 38482016, 2024). "Regarding the input pathways in target cells, the receptors associated with C2 ALOX5+MCs were primarily CD99, SELE, and SPP1, while the receptors related to tumor cells included TWEAK, CEACAM, and CD96." (PMID 39224598, 2024). "Immune checkpoint genes, including CTLA4, CD96, and TIGIT, are enriched in the first layer on the tumour side." (PMID 39350478, 2024). "In vitro analyses revealed that tumor-infiltrating lymphocytes obtained from HPV+ HNSCC cultivated with anti-CD3 and anti-CD96 antibodies had an increased proliferation compared to a culture with anti-CD3 antibodies." (PMID 37046787, 2023). "CD96 interacts with its ligand, CD155, which is widely expressed in various cell types, including T cells, DCs, tumor cells, and many other cell types." (PMID 37345057, 2023). "CD226 can compete with the inhibitory receptors CD96 and T cell immunoreceptor with Ig and ITIM domain (TIGIT) expressed on T cells for binding to CD155 overexpressed in tumor cells to exert anti-tumor effect." (PMID 37312116, 2023).
tumor (continued). "The expression levels of immune checkpoint genes, including CTLA4, CD96, and TIGIT, were also enriched in the first layer (0–250 μm) on the tumor side, indicating an elevated immunosuppressive status of immune cells in this area." (PMID 37337030, 2023). "This pro-adhesive property of CD96 and a higher expression of PVR in certain tumors aids in tumor recognition and tumor cell death by NK cells." (PMID 36674817, 2023). "The impact of BCL9 suppression on promoting CD155 expression by tumor cells was recently demonstrated, providing new insight into the role of BCL9 in regulating CD226 and CD96 immune receptors." (PMID 36717657, 2023). "PD-1, CTLA4, CD96, and TIGIT are important immune checkpoints that are potential targets for tumor immunotherapy." (PMID 36936375, 2023). "CD96 regulates the activities of NK cells and CD8+ T cells and is an important factor in regulating tumor immune function." (PMID 36674817, 2023). "Consistent with suppression of cytotoxic function by CD96 in T cells, 4D5-96z CAR-T cells were found to be less cytotoxic compared with 4D5-z counterparts against tumor cells highly expressing HER2." (PMID 36672244, 2023). "Platelets reduce tumor cell recognition and cytotoxicity by NK cells by reducing the expression of CD112 and CD155 on tumor cells and their related receptors CD226 and CD96 on the NK cells." (PMID 35936717, 2022). "Blockade of CD96 can enhance PD-1/PD-L1 and anti-TIGIT inhibition, leading to increased tumor regression and greater efficacy of immunotherapy." (PMID 36177001, 2022). "In contrast, TIGIT and CD96 are inhibitory receptors, and PVR upregulation in heterogeneous tumor cells results in tumor cell recognition and binding by activating receptor CD226 and the inhibitory receptors TIGIT and CD96." (PMID 35625835, 2022). "A functional role for CD96 wasn’t identified until half a decade later when the interaction between CD96 on NK cells and CD155 on tumor cells was described." (PMID 35812451, 2022). "GEPIA databases manifested that the expression of CD96 was higher in SKCM samples than that of normal skin tissues, and it was significantly correlated with the tumor stage." (PMID 36043142, 2022). "A marked correlation between CD96/TIGIT messenger(m) RNA levels and CD3E/CD8a/CD4, with similar observations at the protein level (i.e., T cells), can be seen across multiple tumor types." (PMID 35812451, 2022). "The third type of binding occurs with CD96, and while less data are available regarding its interaction with CD155 in humans, mice models suggest that the binding promotes tumor escape from the immune system." (PMID 36059606, 2022). "On the other hand, anti-CD96 combined with adriamycin chemotherapy, anti-CTLA-4, or anti-PD-1 exhibited more effective inhibition of tumor metastasis in three different tumor models." (PMID 35606854, 2022). "Other preclinical studies have shown that blocking CD96 in combination with anti-PD1 or anti-CTLA-4 enhanced NK cell infiltration and IFN-γ production, thereby reducing tumor metastases in the lungs for various types of solid tumors." (PMID 34768814, 2021). "Expression of the NK cell receptors DNAM-1, CD96 and NKG2D, the degranulation marker CD107a, and the cytokines IFN-γ and TNF, were similar in NK cells derived from tumor bearing B6-MAITcast MR1 WT and B6-MAITcast MR1−/− mice." (PMID 34362900, 2021). "NK–tumor interactions included HLA-C/KIR2DL4, HLA-E/CD94 (KLD1), TIM3 (HAVCR2)/Galectin-9, CD96-PVR/Nectin1 and TIGIT-PVR/Nectin2." (PMID 33671917, 2021). "When assessing cell type interactions between CD8+ T cells (marker gene: CD8A) and tumor cells (marker gene: EpCAM), most of them showed interactions known to be mediating immunity, including that of CD155 with CD96 between CD8+ T cells and tumor cells." (PMID 34417435, 2021). "Co-inhibitory TIGIT and CD96 compete with co-stimulatory CD226 for their ligands CD155 and CD112 on dendritic cells (DCs) or tumor cells to suppress the anti-tumor immunity of TILs." (PMID 34858835, 2021).
tumor (continued). "The co-inhibitory receptors CD96, TIGIT, PVRIG and the costimulatory receptor CD226 comprise a critical regulatory system for lymphocyte activity and anti-tumor immunity, and they share the same ligands CD155 and PVRL2." (PMID 34174928, 2021). "Other checkpoint inhibitors against CD96, TIGIT or TIM-3 enhance anti-tumor activity in various solid tumors." (PMID 34572387, 2021). "The representative IHC images of normal/tumor and low/high grade tissues from HPA revealed that the degree of staining intensity of CD96, DDB1, IP6K2, PDCL3, TRIM38, and KCNJ15 were in correspondence with our predictions of coefficient." (PMID 34268106, 2021). "This shift was accompanied by an upregulation of TIGIT and CD96, and concomitant reduction in DNAM-1 levels, thus creating a pro-tumor environment." (PMID 33255582, 2020). "PVR and Nectin-2 are expressed by tumor cells as well as myeloid cells, while TIGIT, CD96, and DNAM-1 are expressed on effector lymphoid cells." (PMID 32489646, 2020). "It has been proposed that in the tumor microenvironment the balance between CD155/DNAM-1 and CD155/TIGIT/CD96 contrasting signals contributes to regulate NK cell effector functions." (PMID 32019260, 2020). "Although soluble CD155 (sCD155) contributes to the neutralization of poliovirus infectivity in vitro, it remains undetermined how it is involved in tumor immune responses mediated by DNAM-1, TIGIT, and CD96." (PMID 32040157, 2020). "On the other hand, a combination of Anti-CD96 with doxorubicin chemotherapy, anti-CTLA-4, or anti-PD-1 has shown more efficacy in inhibiting experimental metastases in three different tumor models." (PMID 32117298, 2020). "It has been found that in tumor cells, immune checkpoints can lead to NK cell dysfunction, blocking these immune checkpoints (e.g. TIM-3, NKG2A, CTLA-4, PD-1, KIR2DL-1/2/3, CD96, TIGIT) can restore the function of NK cells." (PMID 33614486, 2020). "All together, this evidence demonstrates that during tumor progression the balance between DNAM-1 and its inhibitory counterparts is deregulated by an up-regulation of TIGIT and CD96, and a concomitant decrease of DNAM-1 expression." (PMID 32019260, 2020). "DNAM-1 has an important role in NK cell-mediated tumor immunosurveillance and shares CD155 and CD112 ligands with TIGIT and TACTILE (CD96)." (PMID 32290478, 2020). "Increased TIGIT and CD96 expression and lower levels of DNAM1 were also detected on ILC1s induced by TGF-β, contributing to the impairment of their anti-tumor response." (PMID 31105707, 2019). "Preclinical studies showed that CD96 blocking combined with anti-PD1 or anti-CTLA-4 enhances NK cell infiltration and IFN-γ production, thus reducing tumor lung metastases." (PMID 32038612, 2019). "Accordingly, antibody blockade of CD96 promotes NK cell production of IFN-γ and leads to improved tumor control of lung metastases in three different mouse models, both alone or, more effectively, in combination with anti-CTLA-4, anti-PD-1, or doxorubicin." (PMID 30250471, 2018). "The tumor sample was divided into groups according to tumor characteristics known to be indicators of cancer progression, and the percentage of CD226+ and CD96+ NK cells was compared between these groups." (PMID 27626490, 2016). "Although CD155 present on tumor cells can induce CD226-dependent immunosurveillance, the expression of CD96 and TIGIT on the same cell can counterbalance CD226 activity." (PMID 27148271, 2016). "Our results showed that the expression of the genes CD96, CD1d, CRTAM, LFA-1 and DNAM1, involved in the interaction of NK cells with target cells such as tumour cells or DCs, increased in patients with favourable prognosis." (PMID 23758773, 2013). "CD96 expressed on NK-cells has been identified as a receptor for CD155 (polio virus receptor) and mediates adhesion of NK-cells to tumor cells, thereby modulating effector function of NK-cells." (PMID 22879978, 2012).